MIR106A (microRNA 106a)
Synonyms: hsa-mir-106a; MIRN106A; mir-106; mir-106a
Gene: MicroRNA gene on chromosome X (134,170,198 to 134,170,278, reverse strand). Ensembl gene ENSG00000284157.
Gene Ontology:
Biological process: miRNA-mediated post-transcriptional gene silencing
Cellular component: RISC complex